CTLA4 (cytotoxic T-lymphocyte associated protein 4)
Diseases named in the same sentence as CTLA4 in open-access papers (continued):
Sharing a sentence is not in itself a finding about the gene and the disease.
tumor (continued). "Combined knockdown of VISTA and CTLA-4 in tumor cells led to increased expression of proinflammatory cytokines in cocultured T cells in vitro, suggesting that the expression of either VISTA or CTLA-4 by tumor cells may significantly inhibit T-cell activity." (PMID 39482534, 2024). "This is because targeting multiple inhibitory immune checkpoints concomitantly often induces stronger anti-tumor effects, which is why PD-1 and CTLA-4 ICI combinations are standard of care in patients with metastatic melanoma, advanced/recurrent NSCLC, malignant pleural mesothelioma, amongst others." (PMID 39339217, 2024). "In addition, treatment with 8 Gy x 3 fractions with CTLA-4 blockade increases tumor-infiltrating CD4+ and CD8+ lymphocytes." (PMID 38778925, 2024). "However, some studies have indicated that the levels of CTLA-4, LAG-3, and TIM-3 originating from cells in patient tumor tissues are associated with survival times post-ICB treatment." (PMID 39528800, 2024). "Furthermore, the CTLA-4/CD80, CD86 axis established between immune cells and tumor cells has been implicated in attenuating anti-tumoral immune responses in the tumor microenvironment." (PMID 38893120, 2024). "Therefore, in our recurrent model, enhanced T-cell expansion during the priming stage in TDLNs was required for an extended anti-tumor effect and was only achieved by the combination of 16 Gy + anti-CTLA4." (PMID 39199612, 2024). "Importantly, no decrease in Treg abundance was observed in our experiments, although Treg depletion by anti-CTLA-4 Ab treatment has been reported to contribute to tumor elimination." (PMID 39106430, 2024). "Moreover, HK3 stimulates monocyte/macrophage infiltration and regulates the expression of immune checkpoint molecules PD1 and CTLA-4 in exhausted T cells, thereby inhibiting immune escape of tumor cells." (PMID 39014460, 2024). "Overall, these findings suggest that Bifidobacterium may promote CTLA-4 blockade and PD-1/PD-L1, improving efficacy against ICIs and promoting tumor control." (PMID 38564002, 2024). "Moreover, We also applied the Immune Phenotype Score (IPS) to predict tumor responses to immune therapy, especially for treatments targeting CTLA-4 and PD-1." (PMID 38977952, 2024). "Consequently, by blocking CTLA-4 at an early stage of the T cell maturation process, we aim to enhance the anti-tumor immune response." (PMID 38928150, 2024). "Furthermore, research in mouse models has demonstrated that the combined treatment of sympathetic nerves and CTLA-4 blockers significantly suppressed tumor growth and enhanced the infiltration of CD8+ T cells at the tumor site." (PMID 38567163, 2024). "The differential requirement of tumor cell IFNGR signaling for CTLA-4 or PD-1 ICB and IFNAR signaling for CD47-SIRPα ICB may be due to the difference of their primary effector targets." (PMID 38982116, 2024). "Additionally, when combined with PD-1 and CTLA-4 inhibitors, mIL12 enhances the effect, significantly increasing the population of tumor-infiltrating central memory T cells." (PMID 39584994, 2024). "Immunotherapeutic approaches like cytotoxic T-lymphocyte-associated protein 4 (CTLA-4), programmed cell death-1/programmed cell death-ligand 1 (PD-1/PD-L1), chimeric antigen receptor (CAR) T cells, tumor antigens, vaccines, and targeted CSC therapies are promising treatments." (PMID 38920716, 2024). "Overexpression of CTLA‐4 may inhibit the activity of antitumor T cells, thereby suppressing tumor immune response." (PMID 39688352, 2024). "Immune checkpoint molecules, such as programmed cell death protein 1 (PD-1), programmed death-ligand 1 (PD-L1), cytotoxic T-lymphocyte-associated protein 4 (CTLA-4), and T-cell immunoglobulin and mucin domain-containing protein 3 (TIM-3), play pivotal roles in regulating anti-tumor immune responses." (PMID 38809277, 2024).
tumor (continued). "Immune checkpoint blockade by specific inhibitors, namely, anti-CTLA-4 and anti-PD-1 inhibitors, is essential in blocking the inhibitory signals of T-cell activation, which allows tumor-reactive T cells to release an effective anti-tumor response." (PMID 39795946, 2024). "Furthermore, we demonstrate that expression of these checkpoints is consequential, since treatment with anti-CTLA-4 antibodies can induce tumor regression in PG/VG plus nicotine-exposed animals." (PMID 39221247, 2024). "High CTLA4+ T cells contributed to poor prognostic outcomes and promoted tumor progression." (PMID 38604154, 2024). "Immune checkpoint inhibitors (ICIs), which target co-inhibitory pathways such as cytotoxic T lymphocyte antigen 4 (CTLA4) and programmed cell death 1 (PD-1) on T cells, as well as programmed death ligand 1 (PD-L1) on tumor and immune cells, can restore T-cell function and enhance antitumor immunity." (PMID 39877377, 2024). "In addition, we have observed that APG‐157 shows complete tumor cell growth suppression in SCCVII murine H&N cancer model when it is combined with anti‐CTLA‐4 antibody which is dependent on CD8+ T cells in the TME." (PMID 38686626, 2024). "However, given that CTLA-4 blockade has exhibited limited efficacy, there is a need to develop innovative mAbs capable of expanding the diversity of tumor-reactive T cells." (PMID 38172595, 2024). "Consistent with human CD8 GZMB+, the human-like CD8 GZMB+ clusters (Cluster0, 1) also had significantly higher Ctla4, Tox and Tox2 expression in the tumor environment injected with Macro CD5L+, while the expression of Pdcd1 (PD1) was not different between the two groups." (PMID 38245530, 2024). "Although CTLA4 expression was found in multiple tumor cells including NSCLC, its function in these cells is largely unknown and is correlated with poor prognosis." (PMID 38384472, 2024). "The immunosuppressive milieu found in solid tumors induces the upregulation of intrinsic inhibitory pathways, characterized by increased expression of inhibitory receptors in T cells when interacting with their corresponding ligands within the tumor microenvironment, such as CTLA-4 and PD-1." (PMID 38727261, 2024). "Furthermore, the study revealed that the combined blockade of PD-1 and CTLA-4 enhanced the infiltration of Teffs, thereby producing a highly favorable ratio of Teffs to Tregs within the tumor." (PMID 39068460, 2024). "Furthermore, the intratumoral introduction of rAd.sT in the immunocompetent breast cancer mice model impeded tumor progression and metastasis in lungs and liver synergistically with anti-CTLA-4 and anti-PD-1 antibodies." (PMID 38281269, 2024). "OC patients with low risk score had a higher PD1&CTLA4 immunophenoscore, higher TMB score, higher HLA-related genes, lower TIDE score, lower tumor escape score and lower immune checkpoints expression, suggesting TRPS as an indicator for predicting immunotherapy benefit." (PMID 38461331, 2024). "ICIs mainly bind to CTLA-4 and PD-1 receptors on the surface of T cells and to PD-L1 receptors on the surface of tumors to relieve the immunosuppression of T cells, thus killing tumor cells." (PMID 39263534, 2024). "In addition to the conventional mechanisms of immunosuppressive responses at the tumor site due to activation of immune checkpoint pathways including the PD-1/PD-L1 Axis and CTLA-4 Pathway, there are other factors involved." (PMID 38397971, 2024). "A study found that CTLA-4+ lymphocyte density was elevated in iCCA compared with peritumoral hepatic tissues, and patients with a high density of CTLA-4+ tumor-infiltrating lymphocytes (TILsCTLA-4 High) showed a reduced OS compared with patients with TILsCTLA-4 Low." (PMID 39845973, 2024). "Additionally, MEDI5752, a bispecific antibody blocking CTLA-4 on PD-L1-positive cells, offers a novel approach with improved tumor targeting." (PMID 39397869, 2024).
tumor (continued). "Additionally, a study using an oral CCR4 antagonist combined with ICB (anti-CTLA-4 or anti-PD-1) therapy in a mouse tumor model demonstrated that the combination therapy is more effective against tumors than monotherapy." (PMID 38500876, 2024). "Additionally, CTLA-4 inhibitors can promote in vivo cross-reactivity and autoantibody synthesis between anti-tumor T cell and normal cell antigens." (PMID 39660124, 2024). "Elevated intra-tumor levels of TIM-3 have also been associated with the suppression of T-cell responses and reduced production of TNF-α, IFN-γ, and GrzB, especially when co-expressed with TIGIT, CTLA-4, or LAG-3." (PMID 38891056, 2024). "Blocking the CTLA-4 axis with anti-CTLA-4 antibodies improves the activity of anti-tumor T cells." (PMID 39795946, 2024). "This systemic immune response affecting the left flank tumor was stronger than when mice with a small left flank tumor received systemic srIL-2 and anti-CTLA-4, together with RT and subcutaneous IL-12 given to the skin on the distant right flank, in mice not bearing a tumor in the right flank." (PMID 39076988, 2024). "Additionally, including PD-1/CTLA-4 inhibitor therapy before TIL therapy has shown benefits by increasing the number of tumor-reactive TILs post-ICI treatment." (PMID 38785789, 2024). "We also demonstrated that this anti-tumor activity was enhanced by anti-CTLA-4." (PMID 39409873, 2024). "Additionally, research has explored the potential of CTLA-4 inhibitors to enhance immune responses against tumor cells." (PMID 39404378, 2024). "By developing a two-site tumor system model, a study found that liver metastasis can inhibit systemic anti-tumor immune response, and proposed that CTLA-4 inhibitors or enhancer of zeste homolog 2 (EZH2) inhibitors combined with PD-1 inhibitors can restore systemic anti-tumor immune activity." (PMID 39493446, 2024). "Furthermore, we showed that the combination of VISTA+/CTLA4+/PD1+ was an independent predictor of prolonged 2-year OS, and the expression of VISTA in tumor cells refers to this association with a favorable prognosis in patients with HGSOC." (PMID 38634058, 2024). "Second, the proportion of CTLA4-positive T-cell subgroups in the peripheral blood and tumor tissues could be higher, making their detection difficult and costly." (PMID 38609844, 2024). "Accordingly, it has been reported that TIGIT, but not other immune checkpoint molecules such as CTLA-4 and PD-1, is associated with NK cell exhaustion in tumor-bearing mice and pts with CRC and that the blockade of TIGIT restored NK cell antitumor activity." (PMID 39126041, 2024). "For example, combined treatment of Polyoxotungstate-1 (POM1; CD39 inhibitor) and anti-PD1 and CTLA-4 antibodies in B16-F10 (melanoma cells) transplanted mice model showed a remarkable reduction in tumor burden and increase in the survival of tumor-bearing mice." (PMID 38347575, 2024). "Although the high-risk group shows lower infiltration of RMCs, higher tumor mutation burden (TMB), and worse prognosis, they are more sensitive to immune therapy with anti-PD1 and anti-CTLA-4, while the low-risk group responds better to immune therapy with anti-PD-L1." (PMID 39014460, 2024). "T-cell priming may also be inadequate at the point of initial tumour antigen presentation, resulting in impaired initiation of anti-tumour immune responses through inhibitory molecules such as CTLA-4." (PMID 38893071, 2024). "In stark contrast, a significant tumor growth delay was seen with the combination of IR and anti-CTLA4 (p < 0.0001; median days to endpoint: anti-CTLA4 6.5 days, 16 Gy + anti-CTLA4 47.5 days) compared to IR and isotype control (p < 0.0001; median days to endpoint: IgG 9 days, 16 Gy + IgG 31 days)." (PMID 39199612, 2024). "Further research is required to determine whether B-cell-mediated immune responses in tumourigenesis and tumour progression are influenced by CTLA-4 expression in dogs." (PMID 38893123, 2024).
tumor (continued). "Patients over 54 years of age with non-superficial tumor, Clark level III–IV, stage III or IV, and with CTLA-4 c.-1577 AA genotype had a 1.80-, 4.87-, 4.37-, 3.43-, and 1.60-times greater chance of recurrence, disease progression, or death related to tumor effects, respectively." (PMID 39596391, 2024). "However, tumor cells acquire this skill and escape immune attack successfully, knowing as immune evasion by upregulation of immunoinhibitory molecules (e.g., PD-1, CTLA-4, TIM3, TIGIT, CD96), or their ligands." (PMID 38440724, 2024). "We recommended an anti-programmed cell death protein 1 (anti-PD-1) plus anti-Cytotoxic T-lymphocyte-associated protein 4 (anti-CTLA-4) combination based on TMB 2-fold greater-than-median TMB in ACC, tumor harboring multiple immunogenic frameshift or splice site mutations, and PD-L1 negativity." (PMID 39451738, 2024). "Radiotherapy can induce anti-tumor immune responses, and a commonly studied approach is the combination of radiotherapy with immune checkpoint inhibitors (ICIs), with the most common being PD-1/PD-L1 and CTLA-4 inhibitors." (PMID 39712010, 2024). "Consequently, these tumours are potentially more responsive to immunotherapies targeting PD‐1/CTLA‐4 pathways." (PMID 39054572, 2024). "We observed a significant delay in tumor growth in all mice and complete tumor regression in approximately 37% of mice treated with DNA-PKi plus immune adjuvants, and 100% tumor regression when paired with anti–PD-1/–CTLA-4 blockade." (PMID 39436696, 2024). "Ipilimumab is as yet the only FDA-approved anti-CTLA-4 anti-tumour drug." (PMID 38475858, 2024). "In addition, RP-1 can express anti-CTLA-4 or other immune co-stimulatory pathway-activating ligands to increase anti-tumor activity by enhancing the systemic immune response against tumor cells." (PMID 39065766, 2024). "Since Treg cells in the TME are a barrier to anti-tumor immune mechanisms and T cell priming, reducing the function of Tregs by potentiating anti-CTLA-4 mediators may be an essential strategy for the development of next-generation anti-CTLA-4 immunotherapy." (PMID 38191571, 2024). "Additionally, it can bind to CTLA-4-expressing T cells and PD-L1-expressing tumor cells, thereby recruiting T cells to tumor sites and intensifying their immunocytotoxicity." (PMID 38735927, 2024). "Blocking the interaction between tumor and T cells such as PD-1/PD-L1 or CTLA-4/B7 axis with immune checkpoint inhibitors could avoid immune evasion and eliminate malignant cells." (PMID 38440724, 2024). "A previous study in mice have shown that the pharmacological inhibition of PAD4 delayed tumor progression and could sensitize cancer cells to combined immunotherapy with anti-PD-1 and anti-CTLA-4 checkpoint inhibitors." (PMID 39001538, 2024). "Indeed, 3LL-ΔNRAS tumours were completely refractory to anti-PD-1 and/or anti-CTLA-4, with the exception of one responder in the anti-CTLA-4 group." (PMID 39322643, 2024). "We also provided preclinical evidence that TGF-β receptor inhibitor suppresses CAFs effectively sensitized colorectal liver and peritoneum metastasis to KN046 that blocking both PD-L1 and CTLA-4, and the tumor responses can be accurately measured in vivo by 68Ga-FAPI PET/CT imaging." (PMID 38175716, 2024). "Immune checkpoint inhibitors such as anti-PD-1 antibodies and anti-CTLA-4 antibodies, regulatory cytokines, and metabolic reprogramming targeting the tumor microenvironment work to reverse the exhausted T cell states, restore their functionality, and reactivate immune responses." (PMID 38629071, 2024). "Correlation between VISTA, PD1, PDL1, CTLA4 expression and tumor infiltrating lymphocytes." (PMID 38634058, 2024). "We examined whether T cells are involved in the observed anti-tumor effects of anti-CTLA-4 Ab treatment." (PMID 39106430, 2024). "Given the prevalence of Tregs in the TdLN of the TC-1 tumor, CTLA-4 blockade may favor Treg over Tconv responses." (PMID 38349740, 2024).
tumor (continued). "Immune checkpoint inhibitors (ICIs) represent another significant cluster in this field, encompassing a range of molecules, including PD-1, PD-L1, and CTLA-4, which exert anti-tumor effects by regulating the interaction of Treg cells with antigen-presenting cells or tumor cells." (PMID 39144829, 2024). "Camelid‐derived, nanobodies targeting PD‐L1 and CTLA‐4, expressed in probiotic E. coli, provided a means of specific delivery achieving selective intra‐tumoural bacterial colonization and therapeutic efficacy in murine tumour models." (PMID 38963257, 2024). "In addition to PD-1/PDL-1, cytotoxic T-lymphocyte antigen-4 (CTLA-4) is another immune checkpoint effector that has recently emerged as a tumor-agnostic biomarker." (PMID 38920700, 2024). "PD‐1 and CTLA4 play critical roles in tumor immune escape by inhibiting T cell activation." (PMID 38737470, 2024). "In comparison to CIN-low tumors, CIN-high murine tumors display a heavily immunosuppressive TME characterized by the presence of dysfunctional CD8+ T cells expressing exhaustion markers such as TOX, PD-1, TIM-3, LAG-3 and CTLA-4; pro-tumor M2-like macrophages and granulocytic MDSCs." (PMID 39544936, 2024). "This heterogeneity may be driven by differential regulation of CTLA-4-related lncRNAs, which in turn could influence tumor behavior and patient prognosis." (PMID 39143529, 2024). "The interaction of immune checkpoint molecules such as cytotoxic T-lymphocyte-associated protein 4 (CTLA-4), programmed cell death protein 1 (PD-1), or B7-H3 receptor with corresponding ligands on tumor cells inhibits their anti-tumor activities, leading to immune suppression." (PMID 38927907, 2024). "In CRC patients, the up‐regulated expression of PD‐1 may indicate poor prognosis, and CTLA‐4 can inhibit the proliferation of T‐effector cells, thereby inhibiting tumor immunity." (PMID 37903487, 2024). "Similarly, another study also used biocompatible injectable hydrogels, this time synthesized from PEG-b-poly(L-alanine), to deliver GM-CSF along with tumor cell lysate antigens and checkpoint antibodies (anti-CTLA-4 and anti-PD-1)." (PMID 37587290, 2024). "In addition, we evaluated the effect of combining Anti-CD47 and Anti-CTLA4 therapy on tumor vascular normalization." (PMID 38398223, 2024). "Dissection of the division of labor between CTLA-4 isoforms to processes such as tumor tolerance and immune evasion may reveal divergent functions which may result in reduced toxicity and should be considered for more effective cancer therapy." (PMID 38053333, 2024). "The co-inhibitory immune checkpoint molecules, e.g., CTLA-4, PD-1/PD-L1, etc., and epigenetic alterations in histone variants, e.g., H3K27me3 that help in immune evasion at tumor microenvironment have not gained much attention in PBTs treatment." (PMID 37605389, 2024). "Additionally, 50% of treated mice experienced complete protection from metastasis and T cell memory protection against future tumor inoculation following PD-1/CTLA-4 signaling inhibition with combined therapy." (PMID 38542199, 2024). "Therefore, tumor-immune cells with CD3 can increase a cytotoxic immune response in contrast to the presence of THCs with CTLA4." (PMID 39499374, 2024). "We recommended dual immunotherapy based on the idea that remodeling the TME by facilitating T cell initiation and trafficking via anti-CTLA-4 could convert the tumor to an immunologically hot state that could be later targeted by anti-PD-1." (PMID 39451738, 2024). "In recent years, the targeting of ICIs such as PD‐1, PD‐L1, and CTLA4 has emerged as a crucial approach in tumor treatment. αPD‐1 can competitively bind to PD‐1 on the surface of T cells with PD‐L1 of cancer cells, thereby enhancing the ability of T cells to kill cancer cells." (PMID 39396375, 2024).